SIRT6 (sirtuin 6)
Diseases named in the same sentence as SIRT6 in open-access papers (continued):
Sharing a sentence is not in itself a finding about the gene and the disease.
tumor (continued). "In agreement with this, we observe increased number of both pPDH+ cells and crypt base columnar (CBC) ISCs (positive for Olfm4) upon SIRT6 loss, which translates into enhanced tumor initiating potential." (PMID 35314684, 2022). "Here, we report that over‐expressed SIRT6 regulates multiple targets to limit tumour progression and cancer‐associated muscle atrophy." (PMID 34212132, 2021). "SIRT6 deficiency is also linked to cancer although the role in cancer is controversial since SIRT6 can act as tumor promoter or suppressor depending on cell type." (PMID 33684691, 2021). "The tumor promoting role of SIRT6 has also been investigated in other cancer types, where reduction of SIRT6 levels is associated to a better response to chemotherapeutics." (PMID 33800266, 2021). "For class III HDACs, a SIRT6 mutation, which is a loss-of-function mutation, was observed in tumour cells and promoted tumour formation." (PMID 34395273, 2021). "In several cancer types, low levels of SIRT6 were associated with marked expression of the pro-survival protein survivin, a condition that correlates with tumor aggression and poor patient survival." (PMID 33800266, 2021). "Based on above results, both the deacetylation and defatty-acylation of SIRT6 were associated with the tumor-promoting effect." (PMID 33995674, 2021). "When evaluated in CRC cell lines, a type of tumor characterized by heavy downregulation of SIRT6, MDL-811 caused a dose-dependent decrease of H3K9Ac, H3K18Ac, and H3K56Ac levels and antiproliferative effects associated with marked G0/G1 cell cycle arrest." (PMID 33800266, 2021). "SIRT6 deficient MEF cells proliferate faster than control wild-type cells and loss of SIRT6 induced faster tumor formation in mice." (PMID 34650436, 2021). "Through its site-specific histone deacetylation activity, SIRT6 promotes chromatin silencing and transcriptional regulation of aging-associated, metabolic, and tumor suppressive gene expression programs." (PMID 34573442, 2021). "Because many metabolic responses of skeletal muscle, such as glucose and fatty acid uptake, are mediated through insulin, its regulation by SIRT6 is an appealing strategy, not only to control tumour growth but also to limit muscle loss." (PMID 34212132, 2021). "It has been known to cause Sirt6 specific Histone H3 deacetylation and accentuate autophagy in various types of cancer cells thereby showing its tumor suppressor effects." (PMID 33442387, 2020). "The loss of SIRT6 in PDAC tumor models was associated with upregulation of LIN28B and consequently increased expression of the let-7 targets HMGA2, IGF2BP1, and IGF2BP3." (PMID 32545414, 2020). "SIRT6 has been reported to regulate inflammation, genome instability, glucose metabolism which are associated with tumor suppressor." (PMID 32158696, 2020). "After demonstrating that several clinically relevant mutations in SIRT6 cause NER deficiency and are present in tumors with high mutation rates across the genome, we propose that SIRT6 is a tumor suppressor during melanomagenesis." (PMID 32789493, 2020). "Conversely, the expression of SIRT6 was associated with higher tumor stage, higher histological grade, platinum resistance, and predicted shorter OS in 104 patients with OC." (PMID 31572453, 2019). "Consistent with this, SIRT6 deficiency resulted in increased tumour growth, where protein synthesis is highly abnormal." (PMID 31372634, 2019). "An important avenue for treatment was explored when the administration of dichloroacetate (DCA) was seen to slow down tumor formation of these SIRT6 deficient mice by inhibiting PDK1, which is also a key target gene for HIF1α." (PMID 29966233, 2018). "The patients with Nu-SIRT6-positive tumors had a 2.087-fold (95% CI' 1.198–3.651) greater risk of shorter OS compared with the patients with Nu-SIRT6-negative tumor." (PMID 30524965, 2018).
tumor (continued). "In other tumors (i.e. skin cancer, hepatocarcinoma, multiple myeloma, and acute myeloid leukemia), SIRT6 can act as a tumor promoter and its overexpression has been associated to poor outcomes." (PMID 30250025, 2018). "It was found that the SIRT6 knockdown-affected genes are associated with cell transformation, tumor invasion and movement of tumor cells." (PMID 29234488, 2017). "In both cases, SIRT6 overexpression delays tumor growth, which is associated with decreased ALDH expression and enzymatic activity, altered glucose and lipid metabolism, and reduced cancer stemness." (PMID 28994177, 2017). "Another finding supporting the pro-proliferative roleof SIRT6 in keratinocytes stems from the proposed inverse association between SIRT6 and the tumor suppressor microRNA34a in keratinocyte differentiation." (PMID 29234488, 2017). "A prior investigation demonstrated that embryonic stem cells and tumor cells deficient in SIRT6 exhibit enhanced glycolysis and compromised mitochondrial respiratory metabolism, mirroring the mitochondrial energy metabolism phenotype observed in DOX-induced injury in the present study." (PMID 40093797, 2025). "Given that UHRF1 is required for SIRT6-deficient BLCA in driving tumor growth, we therefore questioned whether the UHRF1 specific inhibitor, NSC232003, could effectively suppress BLCA." (PMID 39709438, 2024). "Lower levels of SIRT6 are associated with poorer prognosis and increased tumor aggressiveness." (PMID 39349928, 2024). "We thus assessed the impact of SIRT6 deficiency on lactate production in BLCA tumor cells." (PMID 39709438, 2024). "Consistently, down-regulated SIRT6 levels were associated with higher tumor grades." (PMID 39709438, 2024). "Similarly, SIRT3 and SIRT6 exhibit tumor-suppressive functions, with their low expression associated with tumor progression and poor survival, establishing their potential as reliable biomarkers." (PMID 39682281, 2024). "First, we found that SIRT6-deficient tumor cells produced higher extracellular lactate levels than their control cells, which could be abolished with UHRF1-KD." (PMID 39709438, 2024). "Previous research implicated that SIRT6 may exert opposite functions in multiple tumors, and serve as a tumor suppressor or an oncogene." (PMID 39709438, 2024). "As implicated from the xenograft mice model, SIRT6 depletion enhanced tumor growth and angiogenesis, which could be significantly impaired by UHRF1-KD in UMUC-3 cells." (PMID 39709438, 2024). "On the other hand, in SIRT6-deficient cancers, anti-tumor effects may be induced by the activation of SIRT6." (PMID 38203666, 2023). "Likewise, overexpression of SIRT6 reduces cell proliferation and causes cell cycle arrest and apoptosis in vitro and reduces GC cell line tumor growth in nude mice." (PMID 36358890, 2022). "Based on these findings, we believe that in Tu‐Sk.T6Tg mice, over‐expressed SIRT6 might have reduced tumour growth and associated muscle wasting via downregulation of secreted CXCL10 and preservation of plasma level of insulin." (PMID 34212132, 2021). "Although at this stage, we cannot comment on whether favourable effects of SIRT6 over‐expression seen on preventing muscle loss are because of restrained tumour growth in these mice, the observed dual benefits are certainly advantageous." (PMID 34212132, 2021). "The other group of mutations may lead to deregulation of other tumor-suppressive functions of SIRT6." (PMID 32789493, 2020). "A downregulation of SIRT6 is associated with many cancers indicating a role as a tumor suppressor." (PMID 32905943, 2020). "There are several underlying mechanisms involved in the tumor suppressor role of SIRT6." (PMID 33335996, 2020).
tumor (continued). "Additionally, evidence shows that SIRT6 is implicated in the regulation of aerobic glycolysis in tumor cells." (PMID 31591350, 2019). "In addition, SIRT6 has been suggested as a tumor suppressor because loss of SIRT6 is associated with increased tumor formation and shorter survival of cancer patients." (PMID 30524965, 2018). "Furthermore, in colorectal cancer, SIRT6 expression loss associated with glycolytic genes upregulation, promoting cellular transformation, tumour growth and aggressiveness." (PMID 30356832, 2018). "This hypothesis is analogous to that observed with regards to SIRT6 regulation of the Warburg effect, where the loss of SIRT6 tumour suppressive function drives this switch in glucose metabolism." (PMID 26121130, 2015). "Previous studies have implicated that SIRT6 may serve as a tumor suppressor." (PMID 39709438, 2024). "Importantly, SIRT6 is implicated in tumor suppression by repressing transcription programs linked to cell proliferation, inflammation, ribosomal biogenesis, metabolic reprogramming, and genomic instability, and accordingly, down-regulated SIRT6 expression is observed in multiple human cancers." (PMID 34573442, 2021). "Moreover, geneticstudies alone and in combination with compound treatmentin both cellular and animal PDAC models would be required to confirmthe causal link between the observed phenotypes and SIRT6 activationand to conclusively assess the therapeutic potential of 10b in this tumor context." (PMID 34213345, 2021). "Tumor cells can regulate the LD content via the EGFR–PI3K–mTOR and FOXO/SIRT6 pathways, and LDs also regulate the proliferation and growth of tumor cells via membrane lipid and energy formation, which establishes a tight association between LDs and tumor cells." (PMID 31703613, 2019). "Interestingly, the tumor formation promoted by the loss of SIRT6 is oncogene HRAS-independent." (PMID 28406396, 2017). "We not only detected increased expression of Sirt6 following UBCS039 treatment in these cell lines but also found that the Sirt6 expression level varied among these tumor cell lines." (PMID 41530841, 2026). "Some studies have discussed the involvement of Sirt6 in tumor immunity, immunometabolism, immunoregulation and immunosenescence." (PMID 41530841, 2026). "To investigate how Sirt6 impacts immune surveillance in mice with tumor grafts, we measured the levels of immunoregulation-related cytokines, genes and other factors in the peripheral blood and the tumor tissues of these mice." (PMID 41530841, 2026). "Mice that received UBCS039 presented significantly greater expression of the Sirt6, NF-kB, PD-1 and PD-L1 mRNAs in tumor tissue than did mice that received either DMSO or PBS pretreatment." (PMID 41530841, 2026). "Real-time PCR was carried out to determine the mRNA expression of Sirt6 and other genes involved in immunoregulation in tumor tissues from MB-231, HeLa, HCC827 or Lm-3 cell-injected nude mice." (PMID 41530841, 2026). "The aim of the present study was to investigate the function of Sirt6 in immune surveillance and how tumor growth is affected by it." (PMID 41530841, 2026). "The results of the present study suggest that the upregulation of Sirt6 induced by UBCS039 treatment increased the proportion of M2-type macrophages or TAMs in the TME to form an microenvironment conducive to tumor growth." (PMID 41530841, 2026). "We also detected increased Sirt6 expression in tumor tissues from mice after UBCS039 treatment compared with that in the control mice." (PMID 41530841, 2026). "In the present study, we used nude mice (BALB/c FOXN1-/-) to explore the effect of Sirt6 on tumor growth and immune surveillance." (PMID 41530841, 2026). "Increased expression levels of Sirt6, PD-L1, NF-κB, and PD-1 were detected in the tumor tissues of UBCS039-pretreated mice." (PMID 41530841, 2026). "Tumor growth trend analysis further confirmed that SIRT6 overexpression and TFAM knockdown inhibited and slowed tumor growth." (PMID 41362737, 2026).
tumor (continued). "Sirt6 upregulation also activates tumor cells to augment PD-L1, ADO, NF-κB, and PD-1 expression levels and lower IFN-g gamma production." (PMID 41530841, 2026). "We found that increased Sirt6 expression and activity caused by UBCS039 can stimulate tumor growth and increase the expression of PD-1, PD-L1 and ADO and decreased IFN-g in tumor-bearing mice." (PMID 41530841, 2026). "While SIRT3, SIRT4, and SIRT6 are poised to induce tumor-suppressive autophagy, others, such as SIRT2 and SIRT7, are likely to stimulate protective autophagic programs that underlie tumor survival and drug resistance." (PMID 41425553, 2025). "This metabolic rewiring sustains tumor growth and survival, demonstrating SIRT6 as a driver of bioenergetic adaptation." (PMID 41463311, 2025). "Such complexity underscores the necessity for precision medicine approaches when targeting SIRT6, with therapeutic strategies tailored to tumor subtype, molecular background, and treatment regimen." (PMID 41463311, 2025). "In certain malignancies, SIRT6 suppresses tumor growth by regulating key processes such as DNA repair, apoptosis, and autophagy." (PMID 41463311, 2025). "This function is of particular importance in cancer cells, where SIRT6 can act either as a tumor suppressor or, contextually, a tumor promoter depending on its control of glycolysis, oxidative stress, and apoptosis." (PMID 41463311, 2025). "Overexpression of SIRT6, particularly in the HuH7 liver cancer cell line and xenograft mouse model, inhibits tumour growth, suggesting its potential as a therapeutic target for HCC." (PMID 40136715, 2025). "By inhibiting the enzymatic activity of specific glycolytic genes, SIRT6 disrupts the energy metabolism required for rapid tumor cell proliferation." (PMID 41304967, 2025). "Silencing or pharmacological inhibition of SIRT6 suppresses cSCC progression, promoting differentiation, blocking cell cycle progression, and reducing EMT markers, suggesting that SIRT6 supports tumor propagation." (PMID 41463311, 2025). "The metabolic flexibility of SIRT6 enables it to interface with nutrient-sensing pathways and redox homeostasis, thereby positioning it as a critical adaptive node in tumor evolution." (PMID 41463311, 2025). "Their functions in cancer are dualistic: certain SIRTs (e.g., SIRT1) can promote tumor progression in some cancers, while others (e.g., SIRT6) act as tumor suppressors by maintaining genomic stability." (PMID 41213956, 2025). "SIRT6 overexpression significantly ameliorated tumour‐induced wasting and energy expenditure in white adipose tissues (eWAT mass loss: 66% in WT vs. 32% in TG; iWAT mass loss: 69% in WT vs. 40% in TG) through suppression of browning and lipolysis." (PMID 39971710, 2025). "While some studies suggest SIRT6 acts as a tumour promoter by preventing DNA damage and cellular senescence, others indicate that it suppresses tumour growth by inhibiting the ERK1/2 pathway." (PMID 40136715, 2025). "Meanwhile, the HIF-1α/ROS regulatory axis couples the SIRT3- and SIRT6-driven metabolic reprogramming to oxidative adaptation and glycolytic flexibility, enabling tumor cells to maintain mitochondrial function and survive cytotoxic insults." (PMID 41425553, 2025). "Transcriptomic analyses of the gastric inflammation-carcinoma sequence reveal stage-specific SIRT6 activity, with peak expression during intestinal metaplasia and evidence of tumor-suppressive effects through inhibition of cell proliferation and migration." (PMID 41463311, 2025). "Taken together, these studies demonstrate that SIRT6 functions as a tumor suppressor to inhibit the initiation and progression of cancers." (PMID 39955062, 2025).
tumor (continued). "SIRT6 decreased aggravated energy expenditure induced by tumour, especially WAT browning and lipolysis." (PMID 39971710, 2025). "SIRT6 is a tumor suppressor that inhibits cell proliferation and tumorigenesis by partially repressing c-MYC-dependent genes involved in ribosome biogenesis." (PMID 38954215, 2025). "Conversely, in established malignancies, SIRT6 can be co-opted to fuel tumor adaptation by rewiring energy metabolism and sustaining survival under therapeutic stress." (PMID 41463311, 2025). "Ubiquitous overexpression of SIRT6 can effectively attenuate the tumour‐induced lipolysis in adipose tissue, further in vitro experiments suggest SIRT6 can directly prevent tumour‐induced lipolysis in adipocyte." (PMID 39971710, 2025). "Clinically, CAPZA1 and SIRT6 levels correlate with advanced tumor stage and poor prognosis in ccRCC cohorts." (PMID 41354870, 2025). "Equal numbers of unmodified LLC cells were subcutaneously injected into both WT and SIRT6 TG mice to form tumours and lead to cachexia." (PMID 39971710, 2025). "SIRT6 deficiency stabilizes UHRF1, which in turn enhances glycolysis and lactate secretion by upregulating MCT4 and HK2 expression, thereby driving tumor proliferation, migration, and self-renewal." (PMID 41463311, 2025). "Together, our data support a protective role of SIRT6 overexpression against tumour‐driven cachexia, including amelioration of adipose tissue wasting and muscle atrophy." (PMID 39971710, 2025). "This review synthesizes current evidence on the dual roles of SIRT6 in cancer, highlighting its context-dependent functions as both a tumor suppressor and promoter across various malignancies." (PMID 41463311, 2025). "While SIRT1, SIRT2, and SIRT6 can assume opposite functions in relation to the tumor context, SIRT3, SIRT4, and SIRT7 tend to function more in favor of tumors." (PMID 41425553, 2025). "Knockdown of SIRT6 promoted NK cell proliferation and the production of cytotoxic mediators, and the adoptive transfer of SIRT6-null NK cells inhibited tumor growth." (PMID 41425553, 2025). "To analyse how the tumour affects adipose tissue in WT and TG mice on a molecular level, we focused on eWAT tissue, which was better improved than iWAT by SIRT6 overexpression." (PMID 39971710, 2025). "SIRT6 exhibits a context-dependent functional duality in cancer, acting as either a tumor suppressor or an oncogene across different malignancies." (PMID 41463311, 2025). "As a tumor suppressor, SIRT6 represses tumor growth in several cancers including breast and pancreatic cancer, primarily by inhibiting aerobic glycolysis." (PMID 41304967, 2025). "Our previous research has shown that SUMOylation plays a crucial role in modulating deacetylation of SIRT6, which is essential for its tumor suppressive activity." (PMID 38954215, 2025). "Another study showed that SIRT6 plays an important role in maintaining genomic stability and preventing the accumulation of DNA damage, thereby inhibiting tumor progression." (PMID 39845013, 2025). "We also observed an impressive increase of TNFR2 expression under tumour‐bearing condition and found that overexpression of SIRT6 led to a reduction in TNFR2 mRNA levels." (PMID 39971710, 2025). "SIRT6 has been implicated in the regulation of pancreatic ductal adenocarcinoma (PDAC) progression, particularly by promoting tumor cell migration and metastatic dissemination." (PMID 41463311, 2025). "Conversely, SIRT2, SIRT4, and SIRT6 generally exhibit tumor-suppressive functions by inducing apoptosis, inhibiting invasion, and counteracting oncogenic signaling." (PMID 40710366, 2025). "In papillary thyroid cancer, SIRT6 promotes tumor progression and epithelial–mesenchymal transition." (PMID 41463311, 2025). "Pyruvate kinase M2 (PKM2), a nuclear isoenzyme that boosts aerobic glycolysis and encourages tumor growth even in hypoxic environments, can inhibited by SIRT6 through deacetylation." (PMID 39479446, 2024).